TRIM62 (tripartite motif containing 62)
Description:
E3 ubiquitin ligase that plays a role in antifungal immunity by mediating 'Lys-27'-linked ubiquitination of CARD9 downstream of C-type lectin receptors; leading to CARD9 activation, followed by activation of NF-kappa-B and MAP kinase p38 pathways. E3 ubiquitin ligase activity is dependent on E2 ubiquitin-conjugating enzyme UBE2D2.
Synonyms: FLJ10759; DEAR1
Tractability: PROTAC: UniProt records ubiquitination sites on it; ubiquitination databases record sites on it.
Gene: Protein-coding gene on chromosome 1 (33,145,399 to 33,182,059, reverse strand). Ensembl gene ENSG00000116525.
Subcellular location: Cytoplasm
Subcellular location (Human Protein Atlas): Focal adhesion sites; Vesicles
Pathways (Reactome):
Immune System: Interferon gamma signaling
Gene Ontology:
Molecular function: identical protein binding; protein binding; transcription coactivator activity; ubiquitin protein ligase activity; ubiquitin-protein transferase activity; zinc ion binding
Biological process: antiviral innate immune response; positive regulation of antifungal innate immune response; positive regulation of canonical NF-kappaB signal transduction; protein K27-linked ubiquitination; regulation of viral entry into host cell; innate immune response; positive regulation of DNA-templated transcription; protein ubiquitination
Cellular component: cytoplasm; cytosol
Genetic constraint (gnomAD): Loss-of-function variants: 39 observed, 38.32 expected, observed/expected ratio (o/e) 1.02, 90% interval 0.79 to 1.33. The upper end of that interval is the gene's LOEUF score, 1.33, which puts it in group 5 of 6, group 1 being the genes least tolerant of losing a copy. Missense variants: 544 observed, 634.59 expected, observed/expected ratio (o/e) 0.86, 90% interval 0.8 to 0.92. Synonymous variants: 278 observed, 271 expected, observed/expected ratio (o/e) 1.03, 90% interval 0.93 to 1.13.
Homologues: Orthologues: chimpanzee TRIM62 (99% identical), macaque TRIM62 (99% identical), pig TRIM62 (99% identical), mouse Trim62 (99% identical), dog TRIM62 (99% identical), rat Trim62 (99% identical), tropical clawed frog trim62 (85% identical), zebrafish trim62.1 (81% identical), guinea pig TRIM62 (74% identical), rabbit TRIM62 (73% identical), zebrafish trim62.2 (60% identical). Paralogues in human: TRIM8 (20% identical), TRIM46 (19% identical), TRIM2 (18% identical), TRIM65 (17% identical), TRIM3 (17% identical), TRIM71 (17% identical), TRIM41 (17% identical), TRIM24 (17% identical), TRIM7 (17% identical), TRIM36 (16% identical), TRIM67 (16% identical), TRIM39 (16% identical), and 68 more.
Diseases named in the same sentence as TRIM62 in open-access papers:
TRIM62 is named in the same sentence as 21 diseases in open-access papers, as found by Europe PMC text mining. Sharing a sentence is not in itself a finding about the gene and the disease. The quoted sentences say what the papers report.
breast carcinoma (9 papers, 2009 to 2023). "It is reported that TRIM62 was highly expressed in normal epithelia, but mutations were identified in several epithelial cancers, including breast cancer, lung cancer, and ovarian cancer." (PMID 27793172, 2016). "Further studies are needed to identify the possible miRNA associated with the 3-UTR region in TRIM62 and the pathway involved in the HER2 dysregulation to establish it as a possible prognostic marker in breast cancer." (PMID 32341648, 2020). "Meanwhile, TRIM62 was believed to be a prognostic and predictive marker for breast cancers." (PMID 32536816, 2020). "Moreover, studies of breast cancer, lung cancer and acute myeloid leukemia all demonstrated TRIM62 was a tumor suppressor and its low expression was correlated with poor clinical prognosis." (PMID 27793172, 2016). "It is reported that both in breast cancer and lung cancer TRIM62 was as a regulator of EMT." (PMID 27793172, 2016). "Previous studies indicated TRIM62 was a suppressor of EMT in breast cancer and lung cancer." (PMID 27793172, 2016). "However, different from the results found in breast cancer that TRIM62 acted as a master regulator on EMT by blocking TGF-β signaling, the results of Multi-pathway reporter array showed that in CC TGF-β signaling was not significantly affected by TRIM62." (PMID 27793172, 2016).
cervical cancer (4 papers, 2016 to 2021). A primary or metastatic malignant neoplasm involving the cervix. "In vitro and in vivo experiments demonstrated that TRIM62 inhibits the metastasis of cervical cancer by inhibiting the c-Jun/Slug signaling pathway." (PMID 34434284, 2021). "Collectively, these results indicated that overexpressed TRIM62 played a role in inhibiting growth and metastasis of cervical cancer in vivo." (PMID 27793172, 2016). "Moreover, it significantly inhibited proliferation and metastasis of cervical cancer both in vitro and in vivo, which suggested that TRIM62 played as a tumor suppressor in CC." (PMID 27793172, 2016). "Consequently, we firstly examined the association between TRIM62 and EMT markers (α-Catenin and Vimentin) expression in human cervical cancer by IHC." (PMID 27793172, 2016). "It discovered that TRIM62 expression was positively correlated with α-Catenin expression (r = 0.736, P = 0.001), whereas negatively correlated with Vimentin expression (r = -0.612, P = 0.003) in randomly selected cervical cancer sections." (PMID 27793172, 2016). "In addition, TRIM62 is a putative tumor suppressor and the TRIM62 levels represent an important prognostic marker in lung tumor acute myeloid leukemia (AML) and cervical cancer." (PMID 32318585, 2020).
fungal infection (4 papers, 2015 to 2023). "TRIM62 regulates anti‐fungal immunity in the intestine by promoting CARD9‐mediated signalling pathway, and its deficiency may increase susceptibility to fungal infections, such as those caused by Candida albicans." (PMID 35373402, 2022). "TRIM62 as a RING finger E3 ubiquitin ligase induced ubiquitination of CARD9, involving in fungal infection and intestinal inflammation." (PMID 32116696, 2020).
lung carcinoma (3 papers, 2016 to 2022). "In lung cancer, haploinsufficiency of Trim62 synergizes with a K-RasG12D mutation to promote invasiveness and disrupt three-dimensional morphogenesis, which is closely associated with EMT." (PMID 34568024, 2021). "The loss of TRIM62 synergizes with K-Ras mutation, promoting EMT, tumorigenesis, and metastasis in lung cancer." (PMID 36230714, 2022).
gastric cancer (2 papers, 2022). A primary or metastatic malignant neoplasm involving the stomach. "Research has shown that oxidative stress is increased in T cells and decreased in mucous cells in the gastric cancer microenvironment, while TRIM62, MET and HBA1, which are associated with oxidative stress, may be biomarkers reflecting the prognosis of gastric cancer." (PMID 36439106, 2022). "According to the expression of TRIM62, patients with gastric cancer are divided into high expression group (expression higher than 43.3413) and low expression group (expression lower than 43.3413)." (PMID 35659682, 2022). "We found that single cell expression of TRIM62 was increased in tumor samples, which was a protective factor for patients with gastric cancer." (PMID 35659682, 2022). "Our analysis also provides potential biomarkers for prognostic survival analysis of gastric cancer related to oxidative stress: TRIM62, MET, and HBA1." (PMID 35659682, 2022). "After prognostic analysis of the three, TRIM62 was found to be a protective factor for the development of gastric cancer." (PMID 35659682, 2022). "Moreover, TRIM62, MET, and HBA1, which were significantly associated with oxidative stress, may be biomarkers for the prognosis of gastric cancer." (PMID 35659682, 2022).
pancreatic cancer (2 papers, 2023 to 2024). "New experiments have found that M2 macrophage-derived EV miR-193b-3p targets TRIM62 to promote the development of pancreatic cancer, finding a new way to treat pancreatic cancer." (PMID 39165926, 2024).
Viral infection (2 papers, 2020 to 2021). "Viral infection upregulates the expression of TRIM62, which plays important roles in inhibiting ALV and REV replication." (PMID 34516573, 2021). "Altogether, these results strongly suggest that chicken TRIM62 provides host defense against viral infection, and all domains are required for its action." (PMID 32318585, 2020). "When transfected with coiled-coil domain deletion mutant, viral infection decreased the expression of TRIM62 in cells." (PMID 32318585, 2020).
Atrophy (1 paper, 2014). Any weakening or degeneration, especially through lack of use. "In contrast to decreasing levels of Atrogin1 and MuRF1 during the late phase of muscle atrophy, Trim62 levels remained continuously elevated in all atrophy models." (PMID 25263070, 2014). "Our observation that TRIM62 is persistently increased in muscles of critically ill patients at high risk of developing ICUAW and in all atrophy mouse models strengthens this hypothesis." (PMID 25263070, 2014).
cervical squamous cell carcinoma (1 paper, 2016). A squamous cell carcinoma arising from the cervical epithelium. "The expressions of TRIM62 mRNA were markedly down-regulated in both cervical squamous cell carcinoma (SCC) and adenocarcinoma (AC), respectively in comparison with those in NCT." (PMID 27793172, 2016).
tumor (12 papers, 2009 to 2022). "TRIM62 expression was associated with tumor size (P = 0.016), stromal invasion (P = 0.031), recurrence (P = 0.001) and vital status at follow-up (P = 0.001)." (PMID 27793172, 2016). "According to the close association between low expression of TRIM62 and the tumor size as well as stromal invasion in early-stage CC patients, we further investigated the effects of TRIM62 on the proliferation, migration and invasion of CC cells." (PMID 27793172, 2016). "We previously identified the E3 ubiquitin ligase DEAR1/TRIM62 as a tumor suppressor and master regulator of acinar morphogenesis and cell polarity, as well as a negative regulator of TGF-β-mediated EMT and migration in immortalized, non-tumorigenic HMECs26,27." (PMID 36376460, 2022). "Later in 2013, they further elucidated the function of TRIM62, which acted as a chromosome 1p35 tumor suppressor and negative regulator of TGFβ-driven EMT." (PMID 27793172, 2016). "The mean tumor weight and tumor volume of the TRIM62-overexpressed group, SiHa-TRIM62 and HeLa-TRIM62, were significantly smaller than their control group, SiHa-NC and HeLa-NC, respectively." (PMID 27793172, 2016). "The effect of TRIM62 expression on tumor growth and metastasis were further verified by in vivo assays." (PMID 27793172, 2016). "TRIM62 (tripartite motif containing 62) has been found to act as a tumor suppressor of several cancers." (PMID 27793172, 2016). "Furthermore, based on the OncoVar online database, TRIM16, TRIM59, TRIM62, and TRIM71 genes were shown to act as tumor mutation drivers." (PMID 35873464, 2022). "Interestingly, DEAR1/TRIM62 has been reported to suppress tumor metastasis through inhibiting MAPK/JNK-induced SNAI2 expression." (PMID 36376460, 2022). "Significant correlations were identified between low TRIM62 expression and several poor clinicopathologic features in the training cohort, including tumor size (P = 0.036), stromal invasion (P = 0.004), PLNM (P = 0.041), recurrence (P = 0.001) and vital status at follow-up (P = 0.002)." (PMID 27793172, 2016). "Besides, subcutaneous xenograft tumor model and xenograft mouse metastatic model respectively displayed that TRIM62 impeded the growth and metastasis of CC in vivo." (PMID 27793172, 2016). "The inhibitory role of TRIM62 on tumor proliferation might be through regulating cell cycle related proteins CyclinD1 and P27 by targeting c-Jun in CC." (PMID 27793172, 2016). "The inhibitory role of TRIM62 in tumor proliferation might be through regulating cell cycle related proteins CyclinD1 and P27 by targeting c-Jun." (PMID 27793172, 2016). "Furthermore, mechanism study found that the inhibitory role of TRIM62 in tumor metastasis was due to suppression of c-Jun/Slug signaling-mediated EMT." (PMID 27793172, 2016). "Further study is warranted to investigate the potential function of chicken TRIM62 and ARPC2 on REV infection inducing tumor formation." (PMID 32318585, 2020). "In addition, mechanism research indicated TRIM62 could suppress tumor metastasis via inhibiting c-Jun/Slug signaling-mediated EMT, and its inhibitory role in tumor proliferation might be through regulating cell cycle related proteins CyclinD1 and P27 by targeting c-Jun in CC." (PMID 27793172, 2016). "Based on the inhibitory role of TRIM62 in CC progression and MAPK/JNK signaling, we focused on the tumor-promoting role of MAPK/JNK signaling." (PMID 27793172, 2016).
cancer (7 papers, 2009 to 2022). A tumor composed of atypical neoplastic, often pleomorphic cells that invade other tissues. "In mechanism studies, we principally focused on clarifying how TRIM62 suppressed CC metastasis, as local invasion and distant metastasis rather than cell proliferation itself are the cause of 90 % of human cancer deaths." (PMID 27793172, 2016). "In particular, six candidates (TRIM10, TRIM15, TRIM26, TRIM39-RPP21, TRIM62, and TRIM66) are members of the large tripartite motif (TRIM) family that consists of ubiquitin ligases involved in both innate immunity and cancer progression." (PMID 30102725, 2018). "As a member of the same subfamily of TRIM62 (C-IV-1), it was hypothesized that TRIM58 may regulate the malignant phenotype of cancer." (PMID 34434284, 2021).
infection (5 papers, 2018 to 2023). The state of being infected such as from the introduction of a foreign agent such as serum, vaccine, antigenic substance or organism. "A study has confirmed that TRIM62 inhibits the replication of avian leukosis virus, which firstly upregulates TRIM62 in the early stage of infection and then downregulates TRIM62 during the late stage of infection." (PMID 37628607, 2023). "Compared with control, the viral protein levels were significantly increased (p < 0.001) from 48 to 96 h post-infection, and TRIM62 protein levels were also significantly upregulated at 48 and 72 h (p < 0.01)." (PMID 32318585, 2020). "Time course infection of REV in CEF cells showed that the REV mRNA levels were significantly increased (p < 0.001) from 48 to 96 h post-infection, and the TRIM62 mRNA levels were also significantly upregulated at 48 h (p < 0.1) and 72 h (p < 0.1) as compared to that in uninfected CEF cells." (PMID 32318585, 2020).
TRIM62 also shares sentences with these, for which no sentence is quoted: ductal carcinoma in situ (3 papers); infiltrating ductal adenocarcinoma (2); acute myeloid leukemia (1); adenocarcinoma (1); Ductal Carcinoma (1); invasive carcinoma (1); muscle atrophy (1); triple-negative breast carcinoma (1); tumors of the breast (1).